CCL20 (C-C motif chemokine ligand 20)
Diseases named in the same sentence as CCL20 in open-access papers (continued):
Sharing a sentence is not in itself a finding about the gene and the disease.
HIV-1 infection (7 papers, 2007 to 2021). The type species of lentivirus and the etiologic agent of acquired immunodeficiency syndrome (AIDS). "Damaged epithelial surfaces at sites of HIV-1 infection lead to release of CCL20 having anti-HIV-1 properties." (PMID 33659876, 2021). "The CCL20/CCR6 axis has earlier been discussed in the context of HIV-1 infection." (PMID 33659876, 2021). "Thus, CCL20/CCR6 is considered to be a “double-edged sword” concerning HIV-1 infection (Lee and Körner, 2017)." (PMID 33659876, 2021).
myeloma (7 papers, 2014 to 2022). "CCL20 expression has been reported to be upregulated in osteoblasts and osteoclast precursors co-cultured with multiple myeloma cells, and this upregulation contributes to the formation of osteoclasts and osteolytic bone lesions in multiple myeloma patients." (PMID 28851919, 2017). "Indeed, bone marrow levels of CCL3 and CCL20 have been shown to be higher in myeloma patients with increased levels of bone disease." (PMID 28389623, 2017). "It was reported that overexpression of CCl20 and CCR6 was also involved in the recruitment of Th17 in the bone microenvironment of myeloma patients." (PMID 36119497, 2022). "Other chemokines have been shown to be elevated in patients with multiple myeloma including CCL3 and CCL20." (PMID 28389623, 2017). "Other nodules in the network correspond to cytokines with known function in myeloma pathophysiology and/or in osteolytic lesions (IL6, IL1β, CCL2, IL8 and CCL20)." (PMID 25268740, 2014).
nasopharyngeal carcinoma (7 papers, 2014 to 2026). A carcinoma arising from the nasopharyngeal epithelium. "Nasopharyngeal carcinoma (NPC) is a neoplasm related to inflammation; the expression of cytokines, such as CCL3, CCL4, CCL20, IL-1α, IL-1β, IL-6, IL-8, and IL-10, among others, is presumed to be associated with NPC occurrence and development." (PMID 39483474, 2024). "EBV+ cHL cell lines that lacked EBNA1 expression did not have increased CCL20 expression, but cell lines that retained EBNA1, including cases of EBV+ nasopharyngeal carcinoma, had increased CCL20 expression." (PMID 37958391, 2023). "Thus, it can be inferred that naturally nasopharyngeal cancer would express higher CCL20 chemokine which stimulated migration of T regulatory cells, further amplifying the progression of nasopharyngeal cancer." (PMID 35963999, 2022). "Apart of that, the chemokine CCL20 was overexpressed in nasopharyngeal cancer." (PMID 35963999, 2022).
non-small cell lung carcinoma (7 papers, 2013 to 2023). A group of at least three distinct histological types of lung cancer, including non-small cell squamous cell carcinoma, adenocarcinoma, and large cell carcinoma. "The chemokine CCL20 is abnormally expressed in non-small cell lung cancer and plays important roles in tumour cell growth, invasion and metastasis." (PMID 32019546, 2020). "The CCL20/CCR6 axis has been shown to promote non-small cell lung cancer progression." (PMID 23800251, 2013).
renal cell carcinoma (7 papers, 2014 to 2023). "In the tumor microenvironment of renal cell carcinoma, cancer cells are activated by CCL20 secreted by tumor-associated macrophages through Akt activation, followed by epithelial–mesenchymal transition and an acquired migration ability." (PMID 31905918, 2019). "TAMs are involved in tumor cell migration through the activated AKT signaling pathway via the CCL20/CCR6 axis in renal cell carcinoma." (PMID 35841069, 2022). "Another hub-chemokine, CCL20, which showed the most gene alterations, was also found to be able to regulate the migration ability, epithelial-mesenchymal transition, and Akt phosphorylation in the human renal cell carcinoma cell line cells, and thus resulting in the poor prognosis of renal cancer." (PMID 37484803, 2023).
Stroke (7 papers, 2015 to 2025). Sudden impairment of blood flow to a part of the brain due to occlusion or rupture of an artery to the brain. "In our study, 415 mRNAs were found to be associated with the effect of 20(R)-Rg3 on stroke recovery, while the expression of these genes, such as Tagln, Vim, Ptges, Pax1, Cxcl3 and Ccl20, was also significantly altered in our sequencing results." (PMID 35268674, 2022). "Genetic deficiency in Ccr6 significantly diminished the infiltration of γδ T cells, highlighting the important role that chemokine (C-C motif) ligand 20 (CCL20)/CCR6 axis plays for γδ T cell migration in stroke." (PMID 33868300, 2021). "At day 22, most of the measured cytokines were slightly (CINC-1, CINC-2α/β, CINC-3, GM-CSF and VEGF) or markedly (CD54, CD62L, CXCL7, CXCL9, CXCL10, CCL3, CCL5, CCL20) induced by stroke compared to Ctl." (PMID 33204331, 2020). "CCL19 and CCL20 are sensitive to hypoxia, inflammation, and edema in the brain and can be up-regulated in the early stage of cerebrovascular disease; they are important indicators of stroke." (PMID 40003312, 2025). "Recognizing that the ligand‐receptor pair CCL20‐CCR6 plays a key role in the chemotaxis of dendritic cells, effector/ memory T cells and B cells under homeostatic and inflammatory conditions, including stroke and TBI, we focus this section on CCL20." (PMID 32356605, 2020). "However, the expression of CCL2, CCL3, CCL4, CCL7, and CXCL2 was strongly increased after stroke, whereas CCL19, CCL20, and CXCL5 expression levels were not changed." (PMID 26640428, 2015).
Cirrhosis (6 papers, 2010 to 2023). A chronic disorder of the liver in which liver tissue becomes scarred and is partially replaced by regenerative nodules and fibrotic tissue resulting in loss of liver function. "In HCC caused by cirrhosis, myofibroblasts oversecrete CCL20, which regulates aerobic glycolysis-driven HCC through the ERK/PKM2 pathway." (PMID 36231045, 2022). "CCL20 mRNA expression from 32 samples with fibrosis (11 with grade 1, 16 with grade 3 bridging fibrosis, and 5 with grade 4 cirrhosis) was significantly increased (Mann–Whitney two-tailed p < 0.0001) relative to 35 liver samples with normal histology." (PMID 29690903, 2018). "Protein products of the EDG4, CCL20, GPR109A, and GRM8 genes, whose CpG sites are characterized by changes in DNA methylation level in tumor tissue in the setting of cirrhosis and fibrosis, belong to “Signaling by G-protein-coupled receptors (GPCRs)” category." (PMID 36923478, 2023).
ischemic heart disease (6 papers, 2017 to 2025). "Chemokine CCL20 has been linked to ischemic heart disease, specifically acute MI, insofar as levels of CCL20 in the blood of patients with MI are higher than those in healthy individuals." (PMID 40131367, 2025). "Serum CCL20 levels have been associated with ischemic heart disease and are considered potential predictors of HF severity and prognosis." (PMID 40868877, 2025). "The chemokine CCL20, initially identified in the liver, lung, and appendix, is now recognized as being expressed in various tissues and has been linked to ventricular dysfunction and the severity of ischemic heart disease." (PMID 40868877, 2025). "In ischemic heart disease, CCL20 has been demonstrated to have higher circulating levels." (PMID 36012347, 2022). "Furthermore, patients with ischemic heart disease have higher circulating CCL20, and CCL20 is expressed in atherosclerotic plaques." (PMID 35453489, 2022). "It has been uncovered that the serum level of CCL20 is correlated with ischemic heart disease." (PMID 36012347, 2022). "A comparative study to evaluate the CXCL10, CCL20 and CCL22 levels in patients with ischemic heart disease." (PMID 30210493, 2018).
triple-negative breast carcinoma (6 papers, 2016 to 2023). An invasive breast carcinoma which is negative for expression of estrogen receptor (ER), progesterone receptor (PR), and human epidermal growth factor receptor 2 (HER2). "The researchers found that overexpression of CCL20 in triple-negative breast cancer cell lines induced high expression of ABCB1, which further promoted taxanes resistance." (PMID 34569432, 2021). "The expression of CCL20 in triple-negative breast cancer cell lines (MDA-MB-231 and BT549) facilitated tumor migration by upregulating MMP1, MMP-2 and MMP-9." (PMID 34569432, 2021). "In addition, treatment with 200 ng/ml CCL20 significantly enhanced cell invasion and stimulated the secretion of MMP-2 and MMP-9 in BT549 and HCC38 cell lines, which are basal-like/triple-negative breast cancer cell lines, as is the MDA-MB-231 cell line." (PMID 28851919, 2017). "Treatment with CCL20 noticeably promoted cell invasion and the secretion of MMP-2/9 in the basal-like triple-negative breast cancer cell lines, not the luminal." (PMID 28851919, 2017).
airway hyperresponsiveness (5 papers, 2007 to 2025). "Our data show that Miro1 suppresses epithelial induction and maintenance of the inflammatory response to allergen, as Miro1 deletion modestly induces increases in pro-inflammatory signaling, specifically IL-6, IL-33, CCL20 and eotaxin levels, tissue reorganization, and airway hyperresponsiveness." (PMID 37377691, 2023). "Furthermore, genetic ablation of Glrx1 decreases eosinophilic inflammation, as well as the expression of pro-inflammatory NF-κB-related mediators like KC and CCL20, and enhances the resolution of airway hyperresponsiveness and mucus metaplasia in mice with allergic airway inflammation." (PMID 25874776, 2015). "In mouse models of immune response and diseases, CCR6 and/or MIP-3α/CCL20 were required in allergic pulmonary inflammation and contributed to ozone-induced airway hyperresponsiveness and the pathogenesis of cigarette smoke-induced pulmonary inflammation." (PMID 23283206, 2009).
chronic obstructive pulmonary disease (5 papers, 2016 to 2023). A chronic and progressive lung disorder characterized by the loss of elasticity of the bronchial tree and the air sacs, destruction of the air sacs wall, thickening of the bronchial wall, and mucous accumulation in the bronchial tree. "In other respiratory diseases such as chronic obstructive pulmonary disease (COPD), the increased presence of DCs in the lungs correlated with the upregulation of CCR6 on DCs and an increase of the CCR6 ligand (CCL20) in the airways." (PMID 28640917, 2017). "Moreover, in chronic obstructive pulmonary disease (COPD), a disease characterized by chronic airway inflammation, the CCR6/CCL20 axis provides a possible mechanism for the accumulation of dendritic cells in the lungs of patients with COPD." (PMID 37092451, 2023).
Crohn disease (5 papers, 2010 to 2025). A gastrointestinal disorder characterized by chronic inflammation involving all layers of the intestinal wall, noncaseating granulomas affecting the intestinal wall and regional lymph nodes, and transmural fibrosis. "In Crohn’s disease patients, cholecalciferol supplementation was associated with lower serum CCL20 levels, which were unaffected by NOD2 mutations." (PMID 40542081, 2025). "However, oral supplementation of cholecalciferol in patients with Crohn’s disease was found to be associated with lower serum CCL20 levels." (PMID 40542081, 2025). "Additionally, the distribution of genotypes was almost identical between Crohn’s disease patients with low and high serum CCL20 levels, and the absolute levels of CCL20 were comparable among different allele carriers." (PMID 40542081, 2025). "Therefore, any potential influence of Crohn’s disease-associated NOD2 mutations on CCL20 serum levels was ruled out35." (PMID 40542081, 2025). "The distribution of Crohn’s disease-associated variants p.Arg702Trp, p.Gly908Arg, and p.Leu1007fsX1008 was almost identical in Crohn’s disease patients with low (≤ median) and high (> median) CCL20 levels." (PMID 40542081, 2025). "Since MDP-induced CCL20 expression via the TLR5/NOD2 response loop is known to be influenced by Crohn’s disease-specific NOD2 mutations, we speculated that NOD2 mutations might impact systemic CCL20 levels and explain this specificity." (PMID 40542081, 2025). "Therefore, we assumed that cholecalciferol supplementation in patients with Crohn’s disease has the potential to restore the disabled VD pathway involved in suppressing CCL20 in Crohn’s disease by reestablishing an appropriate level of VD receptor expression." (PMID 40542081, 2025). "One can speculate that cholecalciferol supplementation may reactivate VD signaling and induce CCL20 downregulation, potentially by enhancing the particularly low expression of VD receptors in Crohn’s disease." (PMID 40542081, 2025). "In contrast, in patients with Crohn’s disease, VD deficiency had no impact on systemic CCL20 levels, as determined in linear regression modeling [univariable: β (95% CI) = 0.016 (− 0.178, 0.209), p = 0.87]." (PMID 40542081, 2025). "However, the association of cholecalciferol supplementation with lower serum CCL20 levels in patients with Crohn’s disease is in line with this explanation." (PMID 40542081, 2025). "Overall, ulcerative colitis (UC) had a significantly stronger CCL20 release than Crohn’s disease (CD) (+242%, p < 0.01), indicating that the CCL20-CCR6 axis may be more involved in UC." (PMID 30347808, 2018). "Therefore, intestinal CCL20 induction via multiple alternative pathways may outweigh genetic defects in the NOD2 pathway in Crohn’s disease." (PMID 40542081, 2025). "Therefore, the reduced availability of VD receptors may better explain the lack of correlation between higher calcitriol/25-hydroxyvitamin D activation ratios and lower systemic CCL20 levels observed in patients with Crohn’s disease." (PMID 40542081, 2025). "Furthermore, absolute CCL20 levels were comparable between NOD2-mutant and wildtype patients with Crohn’s disease." (PMID 40542081, 2025).
gastritis (5 papers, 2010 to 2025). Inflammation of the stomach. "CCL20/MIP-3α has been known to be expressed in inflamed gastric tissue and plays a role in H.pylori induced gastritis." (PMID 21092330, 2010). "Previous studies have suggested that increased expression of CCL20 and CXCL5 in gastritis tissue can recruit T cells and neutrophils to the gastric mucosal inflammation sites, respectively." (PMID 33426088, 2020). "This study indicated that the development of gastritis required the collaboration of CXCL5 and CCL20, recruiting not only T cells and neutrophils but also activated B cells." (PMID 33426088, 2020).
ischemic stroke (5 papers, 2015 to 2022). A stroke disorder caused by obstruction of blood flow to the brain, due to thrombotic (local blood clot formation) or embolic (due to a blood clot or other material traveling from another site) event. "Macrophage inflammatory proteins (MIPs), MIP-1α (CCL3) and MIP-3α (CCL20), are also involved in inflammatory response after ischemic stroke." (PMID 31514749, 2019). "Among the upregulated genes, Hspa1b, Ccl2, Cxcl2, Ccl3, Serpina3n, Timp1, H19, Hspb1, Ccl20, and Cxcl1 were found to demonstrate significant upregulation in pathological phase of ischemic stroke." (PMID 25861363, 2015). "However, the dysfunction of CCL20 in ischaemic stroke has not been reported before." (PMID 34792838, 2022).
laryngeal carcinoma (5 papers, 2019 to 2023). Carcinoma that arises from the laryngeal epithelium. "CCL20 could also promote cell proliferation and metastasis in laryngeal cancer." (PMID 33123272, 2020). "Reference 92 to “Lu, E.; Su, J.; Zhou, Y.; Zhang, C.; Wang, Y. CCL20/CCR6 promotes cell proliferation and metastasis in laryngeal cancer by activating p38 pathway." (PMID 31146450, 2019). "The correct reference is “Lu, E.; Su, J.; Zhou, Y.; Zhang, C.; Wang, Y. CCL20/CCR6 promotes cell proliferation and metastasis in laryngeal cancer by activating p38 pathway." (PMID 31146450, 2019). "In addition, CCL20/CCR6 promotes cell proliferation and metastasis in laryngeal cancer by activating the p38 pathway." (PMID 31395078, 2019).
non-alcoholic fatty liver disease (5 papers, 2018 to 2025). "Moreover, a recent systematic review and meta-analysis suggested that the chemokines, CCL3, CCL4, CCL5, CCL20, CXCL8 and CXCL11, are implicated in the pathogenesis of non-alcoholic fatty liver disease, post-traumatic stress disorder, and also different types of cancers." (PMID 35242125, 2021). "Moreover, a recent systematic review and meta-analysis suggested that chemokines, CCL3, CCL4, CCL5, CCL20, CXCL8 and CXCL11, are implicated in the pathogenesis of non-alcoholic fatty liver disease, post-traumatic stress disorder, and also different types of cancers." (PMID 34054797, 2021).
renal carcinoma (5 papers, 2016 to 2023). A carcinoma arising from the epithelium of the renal parenchyma or the renal pelvis. "In particular, CCL20 has been produced by different cancer cells as pancreatic, breast and renal carcinoma." (PMID 27322553, 2016). "Finally, c-Met expression was increased in renal cancer patients with bone metastasis and CCL20 was upregulated in the circulation of the same patients supporting the relevance to target c-Met to reduce renal cancer-derived bone metastases." (PMID 27322553, 2016). "Furthermore, high expression of interleukin-11 correlated with poor prognosis in clear-cell renal carcinoma, highlighting the clinical relevance of an early detection of IL-11 and CCL20 in renal carcinoma patients." (PMID 27322553, 2016). "HGF was shown to increase expression of CCL20 in neurons, while in cancer, HGF stimulation induced CCL20 secretion in papillary carcinoma of the thyroid and inhibition of HGF resulted in lower CCL20 levels in a renal cancer model." (PMID 34853656, 2021). "Moreover, T regulatory (Treg) cells, infiltrating renal cancer, express high level of CCR6 and its ligand CCL20 is expressed on tumor cells, representing a homing mechanism for Treg that favours the tumor immune escape." (PMID 27322553, 2016). "In parallel, to further address the clinical relevance of c-Met upregulation during tumor progression, we dosed CCL20 in the serum of renal cancer patients with and without bone metastases and in healthy controls." (PMID 27322553, 2016). "Finally, for a clinical perspective, we reported that CCL20 levels were higher in sera of renal cancer patients with bone metastases than in non-bone metastatic patients, suggesting a potential role of CCL20 in the bone metastases induced by RCC stem cells." (PMID 27322553, 2016).
Salmonella Infections (5 papers, 2011 to 2024). Infections with bacteria of the genus SALMONELLA. "CCL20 expression can be promoted by producing the proinflammatory cytokines TNF-α and IL-1β during Salmonella infection." (PMID 28770173, 2017).
sarcoidosis (5 papers, 2020 to 2025). Sarcoidosis is a multisystemic disorder of unknown cause characterized by the formation of immune granulomas in involved organs. "Sarcoidosis-associated ILC1s also expressed CCL20, which may signal to T helper and B cells through CCR6." (PMID 39225100, 2024). "It is worth mentioning that in the BALF derived from patients with sarcoidosis, an increase of ligands for CXCR3 and CCR6 (e.g., CXCL10 and CCL20, respectively) is seen." (PMID 41376646, 2025). "In a mouse model of SodA-induced sarcoidosis, recombinant human SAA1 serves to balance Th17/Treg in a CCL20-dependent manner, and the blocking of CCL20 could partially reverse the expression of Th17-related cytokines." (PMID 39940756, 2025).